FLG (filaggrin)
Diseases named in the same sentence as FLG in open-access papers (continued):
Sharing a sentence is not in itself a finding about the gene and the disease.
tumor (43 papers, 2012 to 2026). "In the EL4 model, bacteria-colonised tumour-bearing mice show significant filaggrin loss in tumour-adjacent epidermis, whereas antibiotic-treated mice maintain near-normal expression." (PMID 41795941, 2026). "T cell infiltration to the tumor bed was modulated by filaggrin mutational state, since patients with wild-type filaggrin showed significant down-regulation of CD4+ naïve T cells, central memory T cells, and natural killer T cells, while Th1 cells were significantly upregulated." (PMID 37284199, 2023). "Alterations of another recurrently altered gene, FLG, were distributed throughout the entire gene, and most mutations were privately enriched in primary tumors or metastases, indicating that they were passenger mutations that emerged with tumor progression." (PMID 34281583, 2021). "The cream effectively repaired SLS‐induced skin injury by up‐regulating the expression of barrier differentiation‐related proteins FLG and LOR." (PMID 39107974, 2024). "FLG is a tumor inhibitor gene drastically decreased in malignant tumors and is implicated in abnormal glucose absorption and mitochondrial alterations." (PMID 37313463, 2023). "GSEA analysis showed that several tumorigenesis and metastasis-related pathways were indeed enriched in FLG-mutant tumor tissue." (PMID 36046250, 2022). "Assessment of the autophagy marker proteins combined with proteins from the epidermal differentiation cluster (involucrin and filaggrin) is often used for the evaluation of the differentiation status of normal and tumor cells." (PMID 34834228, 2021). "Major components of the tumor microenvironment such as capillaries, human extracellular matrix, a stratified epidermis (involucrin, filaggrin) and basement membrane (laminin 332) are recapitulated in vitro." (PMID 30181613, 2018). "The inhibition of the LOX enzymatic activity in the skin equivalent model induces basement membrane disruption and deregulation of filaggrin and K10 expression of the dermis, preparing a phenotype favorable to tumor development." (PMID 23425977, 2013). "Filaggrin and keratin 10 expression in the tumor center was also higher compared to the tumor margin (0.44±0.22, p<0.001; 1.56±0.51, p<0.05) and to peritumoral tissue (0.62±0.18, p<0.001; 1.19±0.34, p<0.01)." (PMID 22808251, 2012). "Samples within the central tumor tissue of SCC showed significantly elevated mRNA expression of filaggrin (13.60±4.52-fold (mean ± SEM), p<0.05) and keratin 10 (10.83±0.51-fold, p<0.001) compared to normal skin." (PMID 22808251, 2012). "In line with a previous report, we did not observe any recurrent variants of FLG implicated in the tumor progression of NB." (PMID 39338204, 2024). "In addition, we analyzed the tumor mutation burden (TMB) in the TCGA cohort and found that, except for ZNF536 and FLG, the mutation frequency of the remaining genes with the highest mutation frequency was greater in the high-risk group." (PMID 39091494, 2024). "In other words, ERK inhibitor may improve the skin rash of AD by acting on the epidermis and restoring filaggrin expression." (PMID 35408826, 2022). "Moreover, GRHL3 expression in a subset of head and neck cancer patients induces tumour differentiation through induction of its tumour-specific target gene FLG and this differentiation potentially influences anti-cancer therapy responses and patient prognosis." (PMID 35269877, 2022). "Combining FLG-mutant tumor types with clinicopathological features showed that FLG mutation was a protective factor but not an independent protective factor." (PMID 36046250, 2022).
tumor (continued). "There are, however, significant differences between PTMmut and overall mutations, with e.g., hornerin (HRNR, a paralog of FLG) being a top-10 PTMmut gene in 14/31 tumor types and versican (VCAN), collagen III (COL3A1) and XIV (COL14A1) all mutated in 9/31 tumor types." (PMID 33802493, 2021). "To investigate whether PULC treatment could alter the skin moisturizing response, we assessed the effect of PULC1 on protein levels of filaggrin and involucrin in dorsal skin lesions of the DNCB-treated NC/Nga mice." (PMID 30691219, 2019). "Notably, CDC27 and FLG genes were mutated at the single-cell level but not detected in the corresponding tumor tissues, and they could promote cell growth by modulating the inflammatory response." (PMID 38870270, 2024). "The molecules that were differentially expressed in tumor and normal tissues by R software analysis were TMEM79, SMG5, NAA35, SLC45A3, FLG, TMEM254." (PMID 37936239, 2023). "For example, cutaneous SCC typically retains characteristics of squamous differentiation, and we found elevated filaggrin and keratin 10 gene expression in the SCC tissue of the tumor center." (PMID 22808251, 2012). "Filaggrin and keratin 10 expression in the tumor center of SCC was also significantly higher than in the tumor center of BCC (5.50±2.98, p<0.05; 0.39±0.09, p<0.001)." (PMID 22808251, 2012). "Conversely, genes related to epithelial differentiation and keratinization (FLG, FLG2, HRNR, TCHH, KRT73), immune regulation and tumor suppression (HLA-G, UNC5D), and metabolic signaling were downregulated, reflecting loss of tissue integrity and immune control." (PMID 41900972, 2026). "Alterations in FCGBP, FLG, KCNJ12, and KCNJ18 were observed in all tumor samples." (PMID 37182141, 2023). "First, alterations in FCGBP, FLG, KCNJ12, and KCNJ18 were observed in all tumor samples, regardless of the responsiveness towards HIPEC." (PMID 37182141, 2023).
cancer (37 papers, 2014 to 2026). A tumor composed of atypical neoplastic, often pleomorphic cells that invade other tissues. "Although frequent mutations in the FLG/FLG2 genes have been previously observed in other cancers, the mutations were usually considered random (passenger)." (PMID 34900699, 2021). "FLG loss-of-function mutations were associated with higher incidence of HPV-related cancers and pre-cancers that are potentially screening and vaccine preventable." (PMID 24905740, 2014). "It has been reported that hairdressers are exposed to the higher levels of chemicals that result in FLG mutations, which may affect their risk of cancer." (PMID 35510248, 2022). "We, however, hypothesize that the excess risk of HPV-related cancers and pre-cancers among FLG mutation carriers is caused by an impaired epidermal skin barrier due to FLG deficiency that leads to increased retention and penetration of HPV in tissue with eventual cancer development." (PMID 24905740, 2014). "Unsurprisingly, the most frequently mutated matrisome genes across the Pan-Cancer cohort —namely mucin 16 (MUC16) and filaggrin (FLG)—top the list of PTMmut-affected genes too." (PMID 33802493, 2021). "We also identified a number of ‘cancer genes'18 as significantly mutated in PDA, including BCLAF1 (5% of cases), IRF6 (4% of cases), FLG (10% of cases), AXIN1 (5% of cases), GLI3 (6% of cases) and PIK3CA (4% of cases)." (PMID 25855536, 2015). "Nonsynonymous mutations in four cancer-associated genes, CTNNA2 (11.1% vs. 5.8%; log10 p-value = −0.6), FLG (8.9% vs. 4.3%; log10 p-value = −0.6), GNAS (4.4% vs. 1.4%; log10 p-value = −0.5), and BCORL1 (17.0% vs. 11.6%; log10 p-value = −0.5), were more abundant in the case group." (PMID 32566745, 2020). "FLG interacts with MCL1, USP1, C21orf59, MAK, and KIR3DS1 and mucin interacts with ERBB3, SNAI1, TWIST1, TWIST2, and CDH2, all of which, IPA predicted to be associated with cancer." (PMID 31058088, 2019). "Interestingly, many novel cancer-associated genes identified by the excess of missense mutations are large genes with repetitive functional domains: LRP1B, CSMD3, FLG, USH2A and others." (PMID 30453881, 2018). "PCDHGC5, PCDHAC2, SPTA1, XIRP2 and FLG seemed unrelated with cancer based the reference study." (PMID 27835590, 2016). "FLG loss-of-function mutations may lead to a greater susceptibility to HPV-related cancer and pre-cancer due to an impaired barrier function and atopic dermatitis; elevated pH of the stratum corneum; and a low grade skin inflammation." (PMID 24905740, 2014). "We also noted seven genes marked with “caution” in PeCanPIE showing the truncation close to the C-terminal (CUX1, FLCN, FLG, MSH6, NSD1, PRDM9, and USP6), questioning its functional effects in the cancer context." (PMID 35406420, 2022). "FLG mutations were not related to several factors that may be related to cancer risk suggesting that the observed association between FLG mutations and HPV-related cancer and pre-cancer risk is not mediated by pleiotropic effects of FLG mutations on these factors." (PMID 24905740, 2014).
cancer (continued). "When cultured under 3-D at ALI system, the expression of both early and late differentiation markers involucrin and filaggrin, as well as viral late gene L1, were detected in the cornified layer of VIN-ALI, suggesting different HPV genomic status from cancer cells." (PMID 37376685, 2023). "When cultured under a 3-D ALI system, the expression of both early and late differentiation markers involucrin and filaggrin, as well as viral late gene L1, were detected in the cornified layer of VIN-ALI 3-D culture derived, suggesting quite a different HPV genomic status from cancer cells." (PMID 37376685, 2023).
infection (21 papers, 2011 to 2025). The state of being infected such as from the introduction of a foreign agent such as serum, vaccine, antigenic substance or organism. "Such vulnerability of AD patients to infection is based on skin barrier dysfunction caused by defects in structural proteins such as FLG, and immune dysregulation, including decreased levels of antimicrobial peptides, which may also result in susceptibility to oral cavity infection." (PMID 33173085, 2020). "In this context, loss of function mutation in the filaggrin gene breaks the epithelial barrier and causes further cell damage, which could be brought about by repeated scratching behavior or infection, leading to deterioration of AD through activation of such a TLR3-dependent mechanism." (PMID 25171086, 2014). "This aligns with their ability to upregulate key skin barrier genes, including FLG, TGM1, and AQP3, which fortify the cornified envelope to prevent water loss and infection, while boosting hydration via water and glycerol transportation." (PMID 40283895, 2025). "The ex vivo infection model showed that the barrier gene FLG and IVL were generally inhibited in S. aureus infection model." (PMID 33828484, 2021). "Another possibility is that the increased expression of the CASP14 gene is involved in the repair of damage caused by the repression of the FLG and KRT1 genes as a host defense response during infection with T. rubrum." (PMID 30029541, 2018). "For the raft culture, infection was performed at 9 d post-differentiation, which is well ahead of the 19 days it took to acquire a fully differentiated, e.g., filaggrin-positive, upper layers." (PMID 29067282, 2017). "Infection of the filaggrin-positive differentiated cells in the uppermost layer was unproductive, while infection of the proliferating basal cells yielded inclusions containing EB-like organisms, indicating the completion of the developmental cycle." (PMID 29067282, 2017). "In parallel, early events post-infection with ACAM-2000 were investigated in cultured keratinocytes in which filaggrin expression was knocked down via siRNA." (PMID 28081250, 2017). "Notably, 67.7% of patients suffered from an infection in the period in question, due to a compromised immune system, mainly cell immunity, from damage to the protective surface layer of the skin, and a filaggrin deficit." (PMID 32218222, 2020). "Vaccinia-associated luciferase signal was significantly increased in keratinocytes treated with filaggrin-directed siRNA prior to infection, compared with keratinocytes identically pretreated with scrambled control siRNA, possibly implicating filaggrin in rapid necrosis of infected cells." (PMID 28081250, 2017). "Since the effects of filaggrin-directed siRNA appeared congruent with effects of STAT3 inhibition in the same infection system, we evaluated whether filaggrin might intersect with STAT3 signaling in infected keratinocytes." (PMID 28081250, 2017). "At 72 h after infection, increased RORα4 expression significantly induced the expression of early and intermediate differentiation markers (keratin 1/10 and involucrin), as well as granular layer markers (loricrin and filaggrin) at both mRNA and protein levels." (PMID 23922987, 2013). "Filaggrin, MIP-1α/CCL3 and MCP-1 levels were higher in pre-infection supernatants compared to controls." (PMID 36482106, 2022). "Filaggrin, HIF-1α, VEGF, RANTES/CCL5, IL-17A, IL-1β, MIP-1α and MIP-1β/CCL5 levels were higher during and after infection." (PMID 36482106, 2022). "In infection model, keratinocytes exposed to 10 and 100 ng/ml IFN-λ1 for 24 h induced significant FLG mRNA expression." (PMID 33828484, 2021). "Consistent with our qRT-PCR analysis, infection of HDFn cells with ΔNp73β in combination with KLF4 + ΔNp63α led to increased expression of KRT14, KRT5, FLG, and SFN as compared to KLF4 + ΔNp63α with control or control alone." (PMID 31216312, 2019).
infection (continued). "For additional mechanistic insight into potential anti-vaccinia roles for filaggrin, we used an ACAM-2000 in vitro infection system previously established in human HEK-001 keratinocytes." (PMID 28081250, 2017). "The lower FLG expression in NPA cells was associated with a reduction in protein levels, with a 6.7-fold-lower protein content in negative pre-infection samples from the RVI positive group compared to negative control group samples (P = 0.06)." (PMID 36482106, 2022). "When comparing the samples of virus-negative controls against negative pre-infection infants, we observed that several molecules were reduced, including filaggrin (19.3 ± 21.5 vs." (PMID 36482106, 2022). "In addition, the levels of filaggrin, VEGF, MIP-1β, RANTES/CCL5, HIF-1α and IL-1β were identified as infection biomarker molecules with AUC values > 0.72, having the next values of specificity (> 79%) and sensitivity (> 55%)." (PMID 36482106, 2022). "Three days after infection of the HDFn cells with ΔNp73-expressing lentivirus, we harvested cells, isolated RNA, and performed qRT-PCR for keratinocyte genes that are markers of the iKC state (KRT14, KRT5, SFN, and FLG)." (PMID 31216312, 2019). "Interestingly, infection with C. trachomatis serovar L2 of differentiating layers, e.g., K10-positive, but filaggrin-negative yielded mature inclusions harboring all developmental forms, indicating normal progression of the developmental cycle." (PMID 29067282, 2017). "Similarly, phosphorylated forms of STAT3 and TAK1, detected in keratinocyte cytosol 3 hours post-infection, were reduced by filaggrin-specific siRNA but not control siRNA." (PMID 28081250, 2017). "Interestingly, filaggrin levels did not vary over the course of infection in the RVI infants (P > 0.05), which could reflect a permanent dysregulation of this protein in RVI infants compared to controls." (PMID 36482106, 2022). "Interestingly, we found differences in the expression of several immune-barrier molecules (filaggrin, MIP-1α/CCL3, MIP-1β/CCL4 and MCP-1) in NPA supernatants of virus-negative controls compared to negative pre-infection samples of RVI neonates." (PMID 36482106, 2022).
genodermatosis (3 papers, 2012 to 2025). "Taken together, we show that the POMP 5′ UTR mutation associated with KLICK genodermatosis results in reduced POMP expression, which in turn causes reduced levels of proteasome subunits and filaggrin as well as increased ER stress." (PMID 22235297, 2012).
inflammation (2 papers, 2016 to 2025). Aberrant reaction of the microcirculation characterized by movement of fluid and leukocytes from the blood into extravascular tissues. "Chronic inflammation reduces barrier proteins (e.g., filaggrin and loricrin), increases transepidermal water loss, and enhances antigen penetration, exacerbating the disease." (PMID 40871454, 2025). "To assess the relative role of innate versus adaptive immunity in the context of spontaneous skin and lung inflammation caused by filaggrin deficiency, we crossed Flgft/ft and Rag1−/− mice, generating T cell– and B cell–deficient Rag1−/−Flgft/ft mice." (PMID 26299987, 2016).
bacterial infections (1 paper, 2020). "Filaggrin binds with keratin fiber in epithelial cells and is affected by the loss of nerve fiber or substance P. Considering that filaggrin is the main constituent of the skin’s barrier, decreased expression of filaggrin in the skin can cause increased susceptibility to bacterial infections." (PMID 32365623, 2020).
immune dysfunction (1 paper, 2025). "Apart from highly prevalent loss-of-function (LOF) variants in FLG, which codes for the crucial epidermal barrier protein filaggrin, most PADs result in significant immune dysfunction with high risk for severe infections." (PMID 41181176, 2025).
psychiatric disorder (1 paper, 2020). A disorder characterized by behavioral and/or psychological abnormalities, often accompanied by physical symptoms. "Although the enrichment does not reach significance following multiple hypothesis testing comparison, it is worth noting that additional genes are implicated in psychiatric disorders (GABRE, GNRH1, FMO1, FLG, SELE, NQO2)." (PMID 33169669, 2020).
FLG also shares sentences with these, for which no sentence is quoted: Allergy (20 papers); hay fever (7); atopic asthma (4); Alzheimer disease (3); cutaneous melanoma (3); glioblastoma (3); glioma (3); actinic keratosis (2); alopecia areata (2); autosomal recessive congenital ichthyosis (2); colorectal cancer (2); ectodermal dysplasia (2); Fanconi Anaemia (2); Graves disease (2); Hashimoto thyroiditis (2); lung squamous cell carcinoma (2); peeling skin disease (2); prostate carcinoma (2); rhinitis (2); type 2 diabetes (2); adult onset asthma (1); aging (1); airway hyperresponsiveness (1); alopecia (1); autosomal dominant ichthyosis vulgaris (1); basophilic leukemia (1); Becker nevus (1); Becker nevus syndrome (1); biotinidase deficiency (1); Candida infections (1).
A further 60 diseases each share a sentence with FLG in 1 paper.